MPO (myeloperoxidase)
Diseases named in the same sentence as MPO in open-access papers (continued):
Sharing a sentence is not in itself a finding about the gene and the disease.
tumor (continued). "In keeping with this finding, an increased MPO expression was correlated with increased tumor size and advanced lymphatic invasion." (PMID 33763491, 2021). "We found that the PKH26+ puncta in tumor cells largely co-localized with MPO when cells were stained with an MPO antibody." (PMID 33110073, 2020). "Similar to the PKH26+ puncta, MPO+ puncta were also more frequently found in tumor cells cocultured with cytotoxic neutrophils (i.e., TANs, differentiated HL-60 and 32Dcl3 cells)." (PMID 33110073, 2020). "When we investigated infiltrating immune cells in the VI, both CD45+ globoid cells and CD45+MPO+ neutrophils in the VI were greatly decreased in oATP-treated tumor animals compared to aCSF-treated tumor animals." (PMID 32391790, 2020). "We analyzed the distribution and putative tumor biological significance of TANs in a well-characterized, therapy-naïve, European GC cohort using immunohistochemical staining of myeloperoxidase (MPO), and digital image analysis using Definiens Tissue Studio®." (PMID 31741042, 2020). "In a LN229TAZ(4SA) tumor section, the MPO-expressing cells are mostly neutrophils in the necrotic area (green-outlined)." (PMID 33110073, 2020). "The granules contain myeloperoxidase, which is responsible for increasing tumor cellular lipid-based ROS, thereby leading to the ferroptotic cell death." (PMID 33110073, 2020). "These MPO-depleted cells were significantly less capable of inducing tumor cell death than controls when examining via Sytox dye viability assay, concordant with results from pharmacological inhibition." (PMID 33110073, 2020). "Compared with vehicle-treated tumor-bearing animals, there was a moderate decrease in MPO+ cells in the VI in both SB225002- and RS504393-treated tumor-bearing animals, but this difference was also not significant." (PMID 32391790, 2020). "(B-D) 20X images of velum interpositum (B), mediobasal hypothalamus (C), and area postrema (D) of brain from sham animal and tumor animal at 10 d.p.i., with 60X inset shown on the right, along with quantification of MPO+ and total CD45+ cells." (PMID 32391790, 2020). "Overall, these results suggested that tumor cells are able to obtain MPO from neutrophils both in vitro and in vivo." (PMID 33110073, 2020). "(D) Quantification of VI-infiltrating CD45+ globoid and MPO+ cells, comparing tumor aCSF to tumor oATP-treated animals." (PMID 32391790, 2020). "In both conditions, barely any MPO+ puncta were observed in tumor cells when compared to those cocultured with neutrophils directly." (PMID 33110073, 2020). "Accordingly, immunostaining of the tumor tissues for MPO showed a decrease in the number of MPO+ cells in Panc02-sh#5 tumors compared with that of Panc02-shCont tumors." (PMID 32340025, 2020). "NET components like myeloperoxidase (MPO), proteinases, and histones can kill a tumor, inhibit tumor growth, and metastasis." (PMID 33042107, 2020). "Measurement of MPO activity provides an indirect indication of the presence of neutrophils in the tumor microenvironment, since MPO is found in the granulocytes present in the neutrophils." (PMID 32899132, 2020). "An incisional biopsy of the oral mass was performed, the immunohistochemistry showed that the tumor cells tested positive for myeloperoxidase, CD4, BCL-2, KI-67." (PMID 33120806, 2020). "We here compared two MHC-mismatched allorestricted TCR with specificity for two different MPO-derived peptide ligands presented by HLA-B7 and identified by MS immunopeptidomic analyses of tumor samples derived from patients with MPN." (PMID 31316521, 2019). "In our MS-based approach additional MPO epitopes presented on myeloid tumor cells have been identified and selected for stimulation in sHLAm approaches to identify new MPO-specific TCRs." (PMID 31316521, 2019). "In contrast, tumor resection decreased dark-phase myeloperoxidase (Mpo) gene expression (H = 6, p < 0.05; post hoc Bonferroni/Dunn: p < 0.05) relative to the other groups." (PMID 31019214, 2019).
tumor (continued). "In human specimens, CRC patients exhibiting an active CRCSC signal (Snail+IL8+) showed elevated tumor infiltration of MPO+ neutrophils, and high (in the top 10%) MPO expression predicted poor survival of CRC patients." (PMID 30683126, 2019). "In this context, 4T1 tumor-bearing mice exhibited increased circulating levels of myeloperoxidase and cfDNA, which are considered indirect biological markers of NET formation." (PMID 31552036, 2019). "Immunohistochemical analysis from the metastasized tumor and healthy tissues from a control mouse show increased staining for neutrophils and MPO from the tumor sites, confirming that the CRET mechanism is the same as seen in the inflammation case above." (PMID 31163706, 2019). "Hyperprogression was directly correlated with pre-existing myeloperoxidase (MPO)+ myeloid cells, and inversely correlated with programmed cell death-ligand 1 (PD-L1) expression on tumor cells." (PMID 31340855, 2019). "Significantly higher MPO concentrations were detected in the sera of KCM tumor bearing mice treated with the combination of TAB004 + Lip-MSA-IL-2 than in the sera of the mice that were administered the other treatments (P < 0.001)." (PMID 31114758, 2019). "Our data suggest that the increased percent of tumor infiltrating CD45+CD11b+ cells and serum MPO concentrations are associated with the increased survival observed in the mice treated with the combination." (PMID 31114758, 2019). "In fact, although the MPO antigen expression in this work was every time identically for both TCR conditions as the targeted tumor cell lines were the same, the MPO-derived target peptide presentation for MPO2 and MPO5 was obviously different." (PMID 31316521, 2019). "The plasma levels of myeloperoxidase and cfDNA were significantly reduced in 4T1 tumor-bearing mice treated with the IL-1R antagonist." (PMID 31552036, 2019). "Focusing on CD8+ T cells in subsequent assays, all four tumor cell lines with endogenous MPO expression were recognized consistently by TCRF5.4- and TCR2.5D6-transduced T cells, respectively." (PMID 31316521, 2019). "In the heterozygous Cxcr2 knockout PKF2h mice, MPO+ neutrophils and CD11b+Ly-6G+ MDSCs significantly decreased in the tumor nest." (PMID 30659170, 2019). "The pre-treatment with FX-cream ameliorated skin hyperplasia reducing MPO activity, as indicatory of leucocyte infiltration, and skin edema." (PMID 30308980, 2018). "We assayed hepatic levels of CD68 (a marker of macrophagic infiltration) and myeloperoxidase (MPO) (a marker of neutrophil infiltration) in HCC tumor specimens, matching paracancerous specimens, and normal liver specimens." (PMID 29445190, 2018). "Immunohistochemical analysis of MPO+ cells revealed a strong and gradual increase of granulocytes in the lung parenchyma of tumor bearing mice compared to tumor free animals in both genotypes." (PMID 29682184, 2018). "MPO levels in tumor and surrounding tissues were also increased in the model group compared to the other groups and were higher in tumor tissues than in surrounding tissues." (PMID 29245972, 2017). "Indeed, a MPO complete depletion may be an undesirable action, as reported by abrogation studies, since it has been associated with atherosclerosis and a slight increase of tumor formation." (PMID 28448444, 2017). "The tumor-bearing animals exhibited increased levels of plasma DNA and myeloperoxidase in addition to significantly increased numbers of circulating neutrophils." (PMID 28743887, 2017). "On the other hand, MPO positivity is a prominent feature for a tumour of myeloid origin that overrides the unusual and aberrant antigen expression (CD79a, CD99)." (PMID 27019694, 2016). "Beside Fas/FasL, TANs also expressed higher levels of MPO, and the number of MPO+ neutrophils was less in 3LL/shCXCL1 tumor tissues than that in 3LL/NC tumor tissues." (PMID 27446967, 2016).
tumor (continued). "The monomorphic tumour cells revealed positive stainings for Leucocyte Common Antigen (LCA), myeloperoxidase (MPO), CD15 and CD117, associated with a high Ki67 index (over 60%)." (PMID 27019694, 2016). "Exaggerated neutrophil infiltration in tumor-adjacent skin was also confirmed by markedly enhanced detection of neutrophil-derived myeloperoxidase (MPO)." (PMID 26413810, 2015). "Immunohistochemistry staining for MPO in patient tumor and normal skin tissues showed that tumor tissues had more CD11b+Gr1+ cells infiltrating the dermis than normal skin." (PMID 24962779, 2014). "Our observations suggest that MPO catalytic activity is critical during the early stages of tumor development." (PMID 24821130, 2014). "Treatment of mice with N-acetyl lysyltyrosylcysteine amide (KYC), a novel tripeptide inhibitor of MPO, during the inflammatory stage reduced tumor burden." (PMID 24821130, 2014). "On days 3–7 after virus injection, while tumor size decreased and intratumoral MPO activity decreased, peritumor MPO activity increased." (PMID 25525560, 2014). "Their observations were made histologically using myeloperoxidase (like us) and an anti-Gr1 antibody, respectively but in different tumor models." (PMID 25299269, 2014). "Burns first described the lesion in 1811 and King first used the term chloroma in 1853 because the tumor often exhibits a greenish color on exposure to air, owing to the presence of myeloperoxidase in the tumor cells." (PMID 24377982, 2013). "Bromide-dependent chemiluminescence with luminol at low pH has also been shown to be specific towards MPO, and was applied successfully to estimate tumor neutrophil content in a mouse model." (PMID 23861842, 2013). "Levels of MPO activity also correlated with the levels of vascular injury and cytotoxicity measured in both tumour types." (PMID 10952787, 2000). "Following treatment with CA-4-P, neutrophil infiltration into the tumours, measured by myeloperoxidase (MPO) activity, was significantly increased." (PMID 10952787, 2000). "Moreover, tumours from DNase I‐treated PUS7‐overexpressing mice exhibited decreased levels of the NETs markers MPO and CitH3, confirming that DNase I suppresses PUS7‐induced NETs formation in vivo." (PMID 41496500, 2026). "Additionally, NETs immobilize circulating tumor cells (CTCs) via β1-integrin interactions and deliver cytotoxic proteins such as myeloperoxidase (MPO), NE, and MMPs to disrupt tumor membranes and prevent metastasis." (PMID 40805288, 2025). "In addition, immunohistochemical (IHC) staining was performed on tumor tissues to evaluate the expression of inflammation- and malignancy-associated markers, including CD68, MCP-1, MPO, and TGF-β." (PMID 41012537, 2025). "Linking the levels of MPO, NE and H3Cit to the clinical stage of the tumor may lead to the conclusion that they can complement, for example, cfDNA and CTC analyses." (PMID 40801632, 2025). "For instance, specific neutrophil subsets (e.g., N1-polarized neutrophils) can directly kill tumor cells via cytotoxic molecules like elastase and myeloperoxidase or indirectly enhance anti-tumor immunity by facilitating antigen presentation and activating cytotoxic T lymphocytes." (PMID 40709341, 2025). "Overall, these findings suggest that MPO may play a crucial role in tumor immune escape and progression by regulating immune cell infiltration and activity." (PMID 40547041, 2025). "However, loss of myeloperoxidase (MPO) and 12/15-Arachidonate Lipoxygenase (ALOX) in PMN-MDSCs significantly inhibits these tumor-promoting effects." (PMID 41035634, 2025). "It appears MPO plays an important role in promoting tumor growth." (PMID 41254689, 2025). "The marked reduction in tumor ROS observed in both MPO−/− and PAD4−/− mice, as well as following pharmacologic NET inhibition with HCQ, support the interpretation that neutrophils, and specifically NET-associated pathways, are major contributors to the elevated ROS detected in PDAC tumors." (PMID 41462673, 2025).
tumor (continued). "Moreover, TANs directly produce cytotoxic mediators such as reactive oxygen species (ROS) and myeloperoxidase (MPO), thereby inhibiting tumor cell proliferation." (PMID 40787464, 2025). "Conversely, increased MPO activity in malignant conditions may support macrophage-mediated antitumor responses, with some studies linking higher MPO levels to reduced tumor growth and improved survival." (PMID 40895555, 2025). "MPO inhibition resulted in decreased tumor burden and prolonged survival." (PMID 40797324, 2025). "MPO is a primary mediator of the anti‐tumor activity of neutrophils." (PMID 39801751, 2025). "In addition, the heterogeneous staining signals of Ly6G and MPO in the PBS-treated group reflect the variable distribution of neutrophils within the tumor microenvironment." (PMID 39971940, 2025). "Moreover, MPO activity in these MPO−/− and PAD4−/−mice was similar to levels observed in tumor-free WT mice, further supporting that NETs are a major source of intratumoral MPO-specific ROS." (PMID 41462673, 2025). "We observed bimodal expression of MHC-II on CD11b+MPO– macrophages on imaging of tumour sections." (PMID 40523200, 2025). "Beyond direct suppression of inflammatory mediators, HOCl may exert paracrine antagonism of tumor-promoting NF-κB signaling through myeloperoxidase (MPO) derived from innate immune cells." (PMID 41462936, 2025). "Furthermore, CD68+ and MPO+/CD206+ cells with round nuclei (likely M2 macrophages) were generally localized at the tumor periphery, with some in the intratumoral regions, suggesting that most of the infiltrating MPO+ cells were TANs." (PMID 40751595, 2025). "Additionally, MPO enhances the expression of MM-supportive genes in bone marrow stromal cells and suppresses tumour-specific T-cell responses in vitro." (PMID 41303900, 2025). "However, we found statistical relevance for DFS for CD68+CD163+MPO+ cells in the epithelial compartment of tumor distant normal tissue." (PMID 40498004, 2025). "Similar to the tumor microenvironment, a significant decrease in CD4+ PD1+ T cells in the spleen was observed as well as exhausted CD8+ T cells and T regulatory cells when MPO was deficient." (PMID 38367056, 2024). "Therefore, developing nanozymes that possess dual enzyme-like activities of SOD and MPO to simulate the neutrophil enzymatic cascades for tumor therapy is highly valuable albeit quite challenging." (PMID 38388471, 2024). "MPO becomes concerning, as elevated expression is associated with LIHC and LUSC, while providing protective benefits in BLCA, indicating its differing impacts based on tumor type." (PMID 39635438, 2024). "However, isolated MDSCs from tumor-bearing WT mice had a significant increase in ROS levels by L-012 bioluminescence compared to tumor-bearing MPO−/− and healthy WT mice, mirroring the luminol signal." (PMID 38367056, 2024). "While improved immunotherapy outcomes have been observed by decreasing the infiltration of myeloid cells into the PDAC tumor microenvironment, our studies demonstrate that by targeting MPO, we both enhance ICT efficacy and also limit immunosuppression in myeloid cells." (PMID 38367056, 2024). "Therefore, we isolated both neutrophils and MDSCs from the spleen of tumor-bearing WT and MPO−/− mice." (PMID 38367056, 2024). "Furthermore, MPO has been involved in pathways of apoptosis, cell migration, tumour growth and adaptive immunity in cancer." (PMID 38530585, 2024). "Using the bioluminescence reporter lucigenin, production of the ROS superoxide anion was measured; both isolated neutrophils and MDSCs demonstrated significant increase in superoxide anion levels in WT tumor-bearing mice compared to tumor-bearing MPO−/− and healthy WT mice." (PMID 38367056, 2024).
tumor (continued). "In an elegant experimental and molecular characterization study, the mechanism of increased chemotherapeutic effect was found to depend on oxidation of 3-IAA by myeloperoxidase from neutrophils, which subsequently increased reactive oxygen species in tumor cells and hence tumor cell death." (PMID 39759130, 2024). "S100A8/A9 also activates myeloperoxidase (MPO) activation, releases and accumulates oxidized lipids, and upregulates the fibroblast growth factor receptor (FGFR) pathway in tumor cells, causing tumor cells to be released from dormancy, reactivated, and form new tumor foci." (PMID 38404689, 2024). "In this context, MPO‐derived hypochlorous acid may possess anti‐oncogenic potential owing to its ability to induce tumour cell death." (PMID 38923838, 2024). "Myeloperoxidase+ (MPO+) neutrophils and CD11b+Ly6G+ MDSCs infiltration into tumours is reduced in CXCR2 knockout PKF [mice with conditional KrasG12D mutation and knockout of TGF-β receptor type II (Tgfbr2), (LSL-KrasG12D/+; Tgfbr2flox/flox, Ptf1a-Cre] mice compared to control animals." (PMID 38384463, 2024). "However, the mechanism by which MPO activity recruits these myeloid cells into the tumor microenvironment requires further studies." (PMID 38367056, 2024). "Higher numbers of MPO+ macrophages corresponded with an increase in total neutrophils, M1-like MDMs and classical monocytes, supporting the notion that these tumours may be primed for strong innate effector responses." (PMID 36725935, 2023). "The involvement of MPO enzymatic activity in tumour development was also investigated in WT mice." (PMID 37627581, 2023). "Thus, in a recent work, we quantified five biomarkers of NETosis (cfDNA, nucleosomes, citH3, calprotectin, and MPO) in plasma (systemic level) and PF (tumor environment) samples from women with advanced HGSOC and control women." (PMID 36983067, 2023). "Chromatin-bound S100a4 mediates NEPs effect on metastatic outgrowth and has not been found to be attached to NETs; and tumor cell NEPs do not have NET-associated enzymes such as NE or MPO, which are essential for NET functions." (PMID 36973439, 2023). "Important components in NETs, such as MPO and protease, can inhibit tumor growth and metastasis and promote tumor cell death; however, some proteases in NETs can also degrade the extracellular matrix and promote tumor cell extravasation and metastasis." (PMID 37313458, 2023). "Genes PRKCZ (Protein Kinase C Zeta), FGR (Src family protein), KDM4B, MPO, COL11A1, FUT4 (Fucosyltransferase IV), and APEH (acylpeptide hydrolase) are directly associated with tumor aggressiveness, growth, and migration, and invasiveness, resulting in poor clinical outcome in cancer patients." (PMID 38086861, 2023). "Furthermore, MPO upregulates the expression of key MM‐supportive genes in BM stromal cells and reduces tumour‐specific T‐cell activity in vitro." (PMID 37699574, 2023). "Furthermore, we confirm that MPO(myeloperoxidase) was significantly upregulated in COAD patient samples, and its levels were significantly linked to tumor malignancy and clinic outcome." (PMID 37935721, 2023). "Taken together, our data demonstrate that MPO contributes to MM tumour growth, and that MPO‐specific inhibitors may provide a new therapeutic strategy to limit MM disease progression." (PMID 37699574, 2023). "The MPO found in NETs has the potential to kill melanoma cells and slow tumor growth." (PMID 37376417, 2023). "Notably, tumour growth studies in mice treated with a small‐molecule irreversible inhibitor of MPO (4‐ABAH) demonstrated a significant reduction in overall MM tumour burden." (PMID 37699574, 2023). "Specific MPO inhibition with 4‐ABAH significantly reduced tumour burden by 48% after 4 weeks compared to vehicle at tumour end‐point (p = 0.041; mean BLI; vehicle, 3.55 × 107 ± 3 × 106 photons/s, compared with treatment with 4‐ABAH, 1.88 × 107 ± 4.48 × 106 photons/s)." (PMID 37699574, 2023).